PRKAG2 (protein kinase AMP-activated non-catalytic subunit gamma 2)
Description:
AMP/ATP-binding subunit of AMP-activated protein kinase (AMPK), an energy sensor protein kinase that plays a key role in regulating cellular energy metabolism. In response to reduction of intracellular ATP levels, AMPK activates energy-producing pathways and inhibits energy-consuming processes: inhibits protein, carbohydrate and lipid biosynthesis, as well as cell growth and proliferation. AMPK acts via direct phosphorylation of metabolic enzymes, and by longer-term effects via phosphorylation of transcription regulators. Also acts as a regulator of cellular polarity by remodeling the actin cytoskeleton; probably by indirectly activating myosin. Gamma non-catalytic subunit mediates binding to AMP, ADP and ATP, leading to activate or inhibit AMPK: AMP-binding results in allosteric activation of alpha catalytic subunit (PRKAA1 or PRKAA2) both by inducing phosphorylation and preventing dephosphorylation of catalytic subunits. ADP also stimulates phosphorylation, without stimulating already phosphorylated catalytic subunit. ATP promotes dephosphorylation of catalytic subunit, rendering the AMPK enzyme inactive.
Synonyms: AAKG; AAKG2; H91620p; WPWS; CMH6; GSDH
Tractability: Small molecule: a drug acting on it is in phase 2 or 3 trials; a high-quality ligand is known. PROTAC: ubiquitination databases record sites on it; its protein half-life has been measured; a small molecule that binds it is known.
Target class: Kinase; Protein kinase regulatory subunit; Enzyme
Safety:
Unwanted effects reported when the protein is acted on. In parentheses: how it was acted on, where the effect was seen, and who reports it.
heart disease (cardiovascular system; source: Force et al. (2011))
Gene: Protein-coding gene on chromosome 7 (151,556,117 to 151,877,507, reverse strand). Ensembl gene ENSG00000106617.
Subcellular location (Human Protein Atlas): Nucleoplasm
Pathways (Reactome):
Autophagy: Lipophagy; Macroautophagy
Metabolism: AMPK inhibits chREBP transcriptional activation activity; Carnitine shuttle
Immune System: AMPK-induced ERAD and lysosome mediated degradation of PD-L1(CD274)
Neuronal System: Activation of AMPK downstream of NMDARs
Organelle biogenesis and maintenance: Activation of PPARGC1A (PGC-1alpha) by phosphorylation
Signal Transduction: Energy dependent regulation of mTOR by LKB1-AMPK
Vesicle-mediated transport: Translocation of SLC2A4 (GLUT4) to the plasma membrane
Gene Ontology:
Molecular function: ADP binding; ATP binding; cAMP-dependent protein kinase inhibitor activity; cAMP-dependent protein kinase regulator activity; phosphorylase kinase regulator activity; protein binding; protein kinase activator activity; protein kinase binding; protein kinase regulator activity; AMP binding; AMP-activated protein kinase activity
Biological process: glycogen metabolic process; intracellular signal transduction; regulation of fatty acid metabolic process; regulation of glycolytic process; ATP biosynthetic process; positive regulation of gluconeogenesis; regulation of cell cycle; regulation of D-glucose import; regulation of fatty acid oxidation; sterol biosynthetic process
Cellular component: extracellular region; nucleotide-activated protein kinase complex; cytoplasm; cytosol; endoplasmic reticulum lumen; nucleoplasm; nucleus
Genetic constraint (gnomAD): Loss-of-function variants: 25 observed, 60.03 expected, observed/expected ratio (o/e) 0.42, 90% interval 0.3 to 0.58. The upper end of that interval is the gene's LOEUF score, 0.58, which puts it in group 2 of 6, group 1 being the genes least tolerant of losing a copy. Missense variants: 546 observed, 710.43 expected, observed/expected ratio (o/e) 0.77, 90% interval 0.72 to 0.82. Synonymous variants: 285 observed, 274.89 expected, observed/expected ratio (o/e) 1.04, 90% interval 0.94 to 1.14.
Gene-disease validity (ClinGen):
ClinGen rates the evidence that PRKAG2 causes each of these diseases.
PRKAG2-related cardiomyopathy (autosomal dominant): Definitive. A metabolic heart condition characterized by variable cardiac hypertrophy, ventricular pre-excitation, and aberrant glycogen storage in the cardiac tissue due to a pathogenic variant in PRKAG2 that results in a net anabolic effect in cardiac cells.
Homologues: Orthologues: macaque PRKAG2 (99% identical), dog PRKAG2 (95% identical), mouse Prkag2 (93% identical), rat Prkag2 (93% identical), guinea pig PRKAG2 (92% identical), pig PRKAG2 (92% identical), rabbit PRKAG2 (91% identical), tropical clawed frog prkag2 (78% identical), chimpanzee PRKAG2 (71% identical), zebrafish prkag2a (51% identical), Caenorhabditis elegans aakg-2 (25% identical), Caenorhabditis elegans aakg-3 (21% identical). Paralogues in human: PRKAG1 (42% identical), PRKAG3 (40% identical).
Diseases named in the same sentence as PRKAG2 in open-access papers:
PRKAG2 is named in the same sentence as 127 diseases in open-access papers, as found by Europe PMC text mining. Sharing a sentence is not in itself a finding about the gene and the disease. The quoted sentences say what the papers report.
cardiomyopathy (42 papers, 2012 to 2026). A disease of the heart muscle or myocardium proper. "Genetic testing, prompted by a family history of sudden cardiac death (SCD), using a targeted panel sequencing including sarcomere protein gene mutations and other cardiomyopathy-related genes, identified a heterozygous PRKAG2 mutation." (PMID 40671717, 2025). "Biallelic PRKAG2 truncating variants were associated with severe and fatal neonatal cardiomyopathies." (PMID 39273120, 2024). "While the LVH in PRKAG2 cardiomyopathy is often associated with excess glycogen deposition and can be variable in severity, it can also be asymmetric, resembling the pattern seen in HCM caused by mutations in sarcomeric genes." (PMID 37685777, 2023). "PRKAG2 cardiomyopathy: this is a genetic disorder with autosomal dominant inheritance caused by mutations in the PRKAG2 gene, which codes for the regulatory gamma-subunit of AMP-activated protein kinase (AMPK)." (PMID 37685777, 2023). "Clinicians were also reminded to pay attention to the possibility of early onset of atrial lesions in addition to ventricular lesions caused by PRKAG2 cardiomyopathy, and timely intervention treatment." (PMID 35360035, 2022). "PRKAG2 cardiomyopathy is usually associated with ventricular hypertrophy, conduction disease, and progressive glycogen storage." (PMID 35360035, 2022). "Familial ventricular preexcitation in PRKAG2 cardiomyopathy is thought to be associated with Mahaim fibers, which have atrioventricular node-like conduction properties." (PMID 35360035, 2022). "The role of the AMPK pathway in PRKAG2 cardiomyopathy carrying the R302Q mutation remains controversial." (PMID 35360035, 2022). "The causal role of SGLT1 in PRKAG2 cardiomyopathy has been established by evidencing that cardiomyocyte-specific knock down of SGLT1 in this genetic HF model rescued the cardiac phenotype." (PMID 34576016, 2021). "The clinical phenotypes of PRKAG2 cardiomyopathies often overlap with HCM due to sarcomere protein mutations and often leads to misdiagnosis." (PMID 33244021, 2020). "Molecular testing to confirm the diagnosis of PRKAG2 cardiomyopathy and familial screening of at-risk relatives should be a part of the overall management strategy." (PMID 33244021, 2020). "Recently, SGLT1 upregulation was causally linked to PRKAG2 cardiomyopathy that is caused by mutations in the gene encoding the γ2 subunit of AMP-activated protein kinase and cardiac-specific SGLT1 deletion attenuated the cardiomyopathy." (PMID 30258369, 2018). "The majority of cardiomyopathy-causing PRKAG2 mutations are missense substitutions of highly conserved residues within or in close proximity to the CBS motifs of the γ2 subunit of AMPK18." (PMID 29097735, 2017). "Our results extend the clinical spectrum of pathological presentation associated with PRKAG2 defect and suggest that PRKAG2 related cardiomyopathy can mimic HCM on pathologic examination and fiber disarray is not pathognomonic of typical HCM." (PMID 23741347, 2013). "Notably, severe AMPK-activating PRKAG2 mutations such as the R531Q variant result in fatal neonatal cardiomyopathy with prenatal bradycardia and extreme cardiomegaly, mirroring the perinatal lethality and cardiac dysfunction observed in our Pkm1-KO mice." (PMID 41536305, 2026). "Cardiomyopathy caused by PRKAG2 gene mutation is called PRKAG2 cardiomyopathy." (PMID 35360035, 2022). "Expression data showing downregulation of AMPK regulator PRKAG3 could be indicative of altered glycogen storage, with glycogen storage disease and PRKAG2 (isoform of PRKAG3) mutation seen in some cases of cardiomyopathy." (PMID 31724174, 2020). "Advanced conduction abnormalities were associated with TTR-CA, and extreme right axis deviation was rare in our cohort (2%) but described only in patients with Danon disease and PRKAG2 cardiomyopathy." (PMID 41574038, 2026).
cardiomyopathy (continued). "PRKAG2 mutations induce structural changes in AMPK, leading to impaired glucose utilisation in myocytes and subsequent glycogen storage cardiomyopathy." (PMID 40671717, 2025). "Among them, they include Danon disease, Pompe disease (GSD type II), Forbes disease (GSD type III), and PRKAG2 cardiomyopathy." (PMID 41463072, 2025). "PRKAG2 cardiomyopathy is a rare genetic disorder that manifests early in life with an autosomal dominant inheritance pattern." (PMID 39273120, 2024). "Currently, PRKAG2 cardiomyopathy has shown extremely heterogeneous phenotypes, the progression of which over time is still poorly understood, especially regarding phenotype–genotype correlations." (PMID 39273120, 2024). "Mutations in PRKAG2 cause structural changes in AMPK and alter its affinity to AMP, impairing carbohydrate metabolism and ultimately causing storage cardiomyopathy with glycogen deposition within myocites." (PMID 39273120, 2024). "These authors report that increased AMPK activity is responsible for the increased mRNA and protein expression of SGLT1 that further increased glucose uptake in PRKAG2 cardiomyopathy." (PMID 39062954, 2024). "First, we did not include rare LVH etiologies, such as Fabry disease, MELAS, Danon syndrome, PRKAG2 cardiomyopathy, and transthyretin amyloidosis." (PMID 36470931, 2022). "PRKAG2 mutations (OMIM#602743) are responsible for structural changes of AMPK, leading to an impaired myocyte glucidic uptake, and finally causing storage cardiomyopathy." (PMID 36556501, 2022). "All these evidences suggested that glycogen deposits in PRKAG2 cardiomyopathy was due to enhanced expression of GYS1." (PMID 35360035, 2022). "PRKAG2 cardiomyopathy is a rare progressive disease characterized by increased ventricular wall thickness and preexcitation." (PMID 35360035, 2022). "In a genetic model of HF related to constitutive activation of AMPK (model of PRKAG2 cardiomyopathy), myocardial glycogen content was increased alongside higher SGLT1 membrane expression." (PMID 34576016, 2021). "The quantum of literature on PRKAG2 cardiomyopathy and its outcomes have been limited and hence, this 7.0 ± 1.5 year follow up data aims to throw light on the distinctive clinical features, natural history and outcomes of this disease." (PMID 33244021, 2020). "To deep phenotype the PRKAG2 cardiomyopathy patients, we performed cardiac MRI (CMR) on 8 subjects (8/22; 36% ) (AV-1, AIV-8, AIV-11, AV-11, BIV-2, CIII-5, CIV-1 and CIV-2) across three families." (PMID 33244021, 2020). "This study describes the phenotype, genotype and clinical outcomes of a South-Asian PRKAG2 cardiomyopathy cohort over a 7-year period." (PMID 33244021, 2020). "Detailed clinical and genetic evaluation revealed PRKAG2 cardiomyopathy in 22 members in these three families." (PMID 33244021, 2020). "Larger follow up studies and data from PRKAG2 cardiomyopathy patients with implanted devices will throw further light on this risk stratification process." (PMID 33244021, 2020). "PRKAG2 cardiomyopathy must be considered in patients with HCM and progressive conduction system disease." (PMID 33244021, 2020). "Here, we report the morphological expression and clinical course of a cohort of 22 PRKAG2 cardiomyopathy patients belonging to three unrelated families, identified at the Amrita HCM center." (PMID 33244021, 2020). "Adopting such a combined approach, the phenotypic expression of PRKAG2 cardiomyopathy alone would certainly lower the threshold to initiate the discussion of AICD implantation for primary prevention with the patient." (PMID 33244021, 2020). "Clinical manifestations in patient 62 were consistent with the features of PRKAG2-related cardiomyopathy." (PMID 30165862, 2018). "AMPK has been identified to be a regulator of metabolism, survival, and fibrosis, by a recent integrative analysis of PRKAG2 cardiomyopathy iPS and microtissue models." (PMID 30559760, 2018).
cardiomyopathy (continued). "One of the most prominent CMR characteristics of PRKAG2 cardiomyopathy in the present study was global subendocardial hyperenhancement in mid-distal hypertrophic regions, with locally transmural hyperenhancement in the apical region." (PMID 28546535, 2017). "CMR offers advantages for better characterization of PRKAG2 cardiomyopathy in PS and is a valuable aid for diagnosis." (PMID 28546535, 2017). "There is little knowledge in cardiovascular magnetic resonance (CMR) characteristics of PRKAG2 cardiomyopathy." (PMID 28546535, 2017). "We also conducted a phenotype analysis using CMR findings in five patients in the present family, and performed a review of the reported PS cases with CMR findings, to add more knowledge to the CMR characteristics in PRKAG2 cardiomyopathy." (PMID 28546535, 2017). "Proliferation and hypertrophy pathways are found to be involved in the development of PRKAG2 cardiomyopathy." (PMID 28546535, 2017). "Human PRKAG2 cardiomyopathy is now recognized to be highly heterogeneous, variably penetrant, and generally milder than initially reported, an observation typical of how our understanding of monogenic disorders evolves." (PMID 29097735, 2017). "CMR is a valuable tool in detecting diffuse and focal myocardial abnormalities in PRKAG2 cardiomyopathy." (PMID 26496977, 2015). "However, a close form of inherited cardiomyopathy has been linked to the PRKAG2 gene, a master regulator of glucose and lipid metabolism, and one of the major causes of dilated cardiomyopathy, the most common type of cardiomyopathy, is hypertension and ischemic cardiomyopathy." (PMID 22973544, 2012). "PRKAG2 cardiomyopathy may evolve from LVH with preserved EF towards LV dysfunction and dilation, resembling DCM." (PMID 39273120, 2024). "Differential diagnosis between PRKAG2 cardiomyopathy and HCM is based on genetic analysis, as the two diseases may overlap, although the phenotypic expression of both phenocopies is highly variable." (PMID 39273120, 2024). "Early diagnosis of PRS and application of contemporary therapies may hopefully bring PRKAG2 cardiomyopathy towards the low mortality rates and good quality of life that have been reached over the years for sarcomeric HCM." (PMID 39273120, 2024). "A review of the PRKAG2 cardiomyopathy literature is provided alongside the case report." (PMID 39273120, 2024). "However, PRKAG2 cardiomyopathy is different from sarcomeric HCM in that it progresses early to systolic dysfunction and dilated cardiomyopathy." (PMID 37685777, 2023). "Global sub-endocardial hyper-enhancement is a common LGE pattern in PRKAG2 cardiomyopathy." (PMID 34362124, 2021). "Our report also confirms the mid-myocardial LGE pattern in PRKAG2 cardiomyopathy." (PMID 34362124, 2021). "The identification of those PRKAG2 cardiomyopathy patients who could benefit from AICD therapy for primary prevention is still unclear." (PMID 33244021, 2020). "PRKAG2 cardiomyopathy is a rare, early onset autosomal dominant cardiomyopathy with progressive clinical deterioration with worsening left ventricular function and heart failure, premature and severe conduction system disease necessitating permanent cardiac pacing therapy and sudden cardiac death." (PMID 33244021, 2020). "CMR offers promising advantages for evaluation of PRKAG2 cardiomyopathy." (PMID 28546535, 2017). "On the other hand, the present study, together with previous studies by other groups demonstrated that SGLT1 is substantially expressed in the myocardium and actually contributes to the pathogenesis of certain types of cardiac diseases, such as PRKAG2 cardiomyopathy." (PMID 26121582, 2015). "Our finding of both diffuse and non-symmetric distribution of LVH in the same family may be explained by the generally progressive nature of LVH in PRKAG2 cardiomyopathy during follow-up, and the varying age of disease onset." (PMID 26496977, 2015).
cardiomyopathy (continued). "The course of the disease in PRKAG2 cardiomyopathy in our series seems to be related to the site of mutation in the PRKAG2 gene, with severe complications found in carriers of PRKAG2 Phe293Leu, His530Arg, and Val336Leu variants, and not in carriers of the Arg302Gln PRKAG2 variant." (PMID 40149727, 2025). "Heart organoids have been used to explore the connections between metabolism and transcription regulation in protein kinase adenosine monophosphate-activated non-catalytic subunit gamma 2 (PRKAG2) cardiomyopathy caused by missense mutations in the PRKAG2 regulatory subunit." (PMID 37560538, 2023). "There is no specific therapeutic management for PRKAG2 mutations-related cardiomyopathy at present." (PMID 36556501, 2022). "A next-generation sequencing genetic analysis with a cardiomyopathy dedicated gene panel (INVITAE laboratory, United States) was performed in all three family members, identifying a missense pathogenic variant (c.905G>A, Arg302Gln, heterozygous) in the PRKAG2 gene." (PMID 36556501, 2022). "Thus, atrial impairments might occur in the early stage of PRKAG2 cardiomyopathy." (PMID 35360035, 2022). "The mean (±SD) number of genes per panel was 33±25, including 8±0.3 sarcomere genes, 4±2 storage cardiomyopathy, and RASopathy genes (LAMP2, PRKAG2, TTR, GLA, PTPN11, RIT1, and RAF1) and 22±23 other genes (range, 0–75)." (PMID 30681346, 2019). "Extreme right axis deviation was rare (18 cases, 2%) and extremely specific for Danon disease (Sp 93%), PRKAG2 cardiomyopathy (Sp 92%), metabolic disease (Sp 90%), and Noonan syndrome (Sp 85%)." (PMID 41574038, 2026). "To date, only few cases of PRKAG2 cardiomyopathy have been described by CMR, and no specific pattern has been identified." (PMID 39273120, 2024). "Since no specific guidelines for PRKAG2 cardiomyopathy are available, the approach to the disease commonly refers to the ESC guidelines for the diagnosis and management of HCM." (PMID 39273120, 2024). "The actual prevalence of PRKAG2 cardiomyopathies has not been properly investigated and only about 200 cases have been reported worldwide so far." (PMID 33244021, 2020). "Other clinical reports document the absence of LVH with this or other PRKAG2 mutations, suggesting that neither LVH nor pre-excitation are universal features of human PRKAG2 cardiomyopathy." (PMID 29097735, 2017). "There are no known precision-based therapies for PRKAG2 cardiomyopathy." (PMID 37685777, 2023). "There are no studies published on PRKAG2 cardiomyopathies from the South Asian region." (PMID 33244021, 2020).